IGHV1-69-2 (immunoglobulin heavy variable 1-69-2)
Description:
V region of the variable domain of immunoglobulin heavy chains that participates in the antigen recognition. Immunoglobulins, also known as antibodies, are membrane-bound or secreted glycoproteins produced by B lymphocytes. In the recognition phase of humoral immunity, the membrane-bound immunoglobulins serve as receptors which, upon binding of a specific antigen, trigger the clonal expansion and differentiation of B lymphocytes into immunoglobulins-secreting plasma cells. Secreted immunoglobulins mediate the effector phase of humoral immunity, which results in the elimination of bound antigens. The antigen binding site is formed by the variable domain of one heavy chain, together with that of its associated light chain. Thus, each immunoglobulin has two antigen binding sites with remarkable affinity for a particular antigen. The variable domains are assembled by a process called V-(D)-J rearrangement and can then be subjected to somatic hypermutations which, after exposure to antigen and selection, allow affinity maturation for a particular antigen.
Synonyms: IGHV1-f; IGHV1F
Gene: Immunoglobulin variable (V) gene on chromosome 14 (106,737,110 to 106,737,547, reverse strand). Ensembl gene ENSG00000281990.
Subcellular location: Secreted; Cell membrane
Gene Ontology:
Molecular function: antigen binding
Biological process: immunoglobulin mediated immune response
Cellular component: extracellular region; plasma membrane
Homologues: Orthologues: mouse Ighv14-2 (66% identical), mouse Ighv14-1 (64% identical), mouse Ighv1-50 (63% identical), mouse Ighv1-53 (62% identical), mouse Ighv1-55 (62% identical), mouse Ighv1-64 (62% identical), mouse Ighv1-74 (62% identical), mouse Ighv14-4 (62% identical), mouse Ighv1-59 (62% identical), mouse Ighv1-66 (62% identical), mouse Ighv1-69 (62% identical), mouse Ighv1-77 (62% identical), and 47 more. Paralogues in human: IGHV1-24 (88% identical), IGHV1-2 (77% identical), IGHV1-3 (77% identical), IGHV1OR15-1 (76% identical), IGHV1-46 (75% identical), IGHV1-18 (74% identical), IGHV1OR15-9 (74% identical), IGHV1-69 (73% identical), IGHV1-69D (73% identical), IGHV1OR21-1 (72% identical), IGHV1-45 (70% identical), IGHV1-58 (68% identical), and 65 more.